EZH2 (enhancer of zeste 2 polycomb repressive complex 2 subunit)
Diseases named in the same sentence as EZH2 in open-access papers (continued):
Sharing a sentence is not in itself a finding about the gene and the disease.
melanoma (continued). "Additionally, these cells exhibited amplification of the transcription factor NFATC2, which is a recently-discovered gene controlling the EMT-like/invasive melanoma program by regulating downstream targets such as c-Myc, FOM1, and EZH2." (PMID 34837846, 2022). "The EZH2-mediated elevation of H3K27me3 has been described to be involved in epigenetic silencing of the tumor suppressor genes RUNX3 and CDH1 in advanced-stage human melanoma tissues." (PMID 35163453, 2022). "EZH2 inhibitors can rescue MHC class I transcription and counteract melanoma dedifferentiation." (PMID 36397155, 2022). "The antagonistic relationship between SWI/SNF and EZH2, and possibly other transcription and epigenetic factors, may potentially be exploited therapeutically in SWI/SNF disrupted melanoma." (PMID 35323214, 2022). "Importantly, combined inhibition of NFATc2 and EZH2 (i.e., AM404+GSK126, respectively) reversed melanoma phenotype switching overnight." (PMID 34604096, 2021). "On the basis of our data, we suggest that expression of PTENP1-AS is induced by the TF C/EBPB in BRAFi resistant melanoma cell lines, which results in transcriptional suppression of PTEN through the recruitment of EZH2 with subsequent formation of H3K27me3 and DNA methylation of the PTEN promoter." (PMID 34040017, 2021). "Notably, EZH2 inactivation reversed the drug-resistant phenotype and amplified the effects of anti-CTLA-4 and IL-2 immunotherapy in melanoma mouse models, thus blocking CM growth and dissemination." (PMID 34575678, 2021). "It is therefore not surprising that EZH2 and NFIB overexpression is associated with invasion and adverse prognosis in melanoma, as EZH2 silences multiple tumor suppressor genes." (PMID 33870460, 2021). "miR-31 host gene (MIR31HG) lncRNA is upregulated in OIS upon BRAF overexpression, binds directly to SUZ12 polycomb repressive complex 2 subunit and EZH2, thus is required for the repression of the INK4A locus, whereas knockdown of MIR31HG promotes a p16INK4A-dependent senescence of melanoma cells." (PMID 34638331, 2021). "EZH2, as well as CDKN1C, have also been recognized as promising biomarkers for treating melanoma." (PMID 32308561, 2020). "Mir-137 can inhibit the migration and invasion of melanoma cells 45–47 by targeting various mRNAs such as PIK3R3, TBX3, c-Met, YB1, EZH2, and MITF, and inhibit the proliferation and promote the apoptosis of melanoma cells by competitive binding to genes such as SLC1A5, GLO1, CDK6, etc.." (PMID 33194692, 2020). "Another study found that EZH2 inactivation reversed the resistance to anti-CTLA-4 and IL-2 immunotherapy and suppressed melanoma growth in a consequence of accumulating IFN γ, producing PD-1 low CD8+ T cells and PD-L1 downregulation on melanoma cells." (PMID 32708698, 2020). "High expression of EZH2 and poor expression of lncRNA GAS5 and CDKN1C was observed in melanoma tissues and found to be correlated with the reduction in survival expectancy of melanoma patients." (PMID 32308561, 2020). "In order to investigate the potential predictive value of H3K27me3 and EZH2 expression concerning responses to ICB, we analyzed their expression patterns in melanoma metastases of 44 patients biopsied before the start of an immunotherapy with an anti-PD-1 antibody." (PMID 32041674, 2020). "Thus, the present study assessed the functions of lncRNA GAS5, EZH2, and CDKN1C in the oxidative stress of melanoma cells." (PMID 32308561, 2020). "BRN2 is also required for outgrowth of melanoma metastases in mouse xenografts and can epigenetically reprogram melanoma cells via up-regulation of the H3K27 methyl transferase EZH2." (PMID 30804224, 2019). "In melanoma, CASC15 may recruit EZH2, and EZH2 could subsequently directly bind to the promoter of PDCD4 in melanoma cells and inhibit PDCD4 expression." (PMID 31620370, 2019).
melanoma (continued). "Strikingly, overexpression of LINC-PINT significantly reduced melanoma cells progression via downregulating the potential target genes CDK1, CCNA2, AURKA, and PCNA through recruiting EZH2 protein, which in turn mediated the trimethylation of H3K27 of promoter regions of target genes." (PMID 31921860, 2019). "Meanwhile, potent molecules selectively targeting EZH2 enzymatic activity have been discovered, including EPZ005687, EPZ-6438, EI1, UNC1999, and GSK126, which also exerts significant anti-tumor effects in distinct melanoma subsets." (PMID 31921860, 2019). "Recent studies have shown EZH2 to be an oncogene in BRAF-driven melanoma, and combination therapy of the BRAF inhibitor vemurafinib with JQ1 or DNA methyltransferase inhibitor decitabine displayed efficacy in pre-clinical melanoma models." (PMID 30340362, 2018). "Ezh2 inactivation reversed this resistance and synergized with anti-CTLA-4 and IL-2 immunotherapy to lead to intratumorally accumulation of IFN-γ-producing PD-1low CD8+ T cells and PD-L1 downregulation to suppress melanoma growth." (PMID 29556394, 2018). "The ulceration rate in melanomas harboring EZH2 gain was 35.3%, whereas in melanomas without EZH2 gain was 69% (P = 0.001)." (PMID 29202777, 2017). "The sensitivity of melanoma cell lines and patient-derived xenograft (PDX) models containing BRAF V600E mutation with or without EZH2 gain to vemurafenib (BRAF inhibitor), GSK2816126 (EZH2 inhibitor) and a combination of both agents was evaluated." (PMID 29202777, 2017). "Given the central role of gene methylation in tumorigenesis, EZH2 and BRAF may cooperate to promote the initiation and progression of melanoma." (PMID 29202777, 2017). "EZH2 contains the catalytic histone lysine methyl transferase subunit of the polycomb repressive complex 2 (PRC2), which plays a role in maintenance of the stem cell-like state of cancer cells and in the progression of malignant melanoma." (PMID 28265786, 2017). "Transfer of wild-type (WT) but not Ezh2−/− Pmel-1 TN repressed the growth of pre-established B16 melanoma in lymphodepleted mice." (PMID 29242551, 2017). "Intriguingly, we also observed up-regulation of E-Cadherin in EZH2 inhibitor-treated IGR1 cells, suggesting that EZH2 may in regulate EMT in a subset of melanomas." (PMID 25671303, 2015). "Although the basis for increased sensitivity of EZH2 mutants is understood, it was not clear why some melanomas with WT EZH2 were also partially sensitive." (PMID 26304929, 2015). "In this study we have examined the putative functions of EZH2 GOF mutants in both melanoma cells and non-tumorigenic cells." (PMID 25671303, 2015). "Further studies are needed to define the relationship between EZH2 and MAP kinase signaling but these results suggest that combining BRAF and EZH2 inhibitors may provide an effective treatment strategy for melanoma." (PMID 26304929, 2015). "In contrast, we have found that only exogenously expressed EZH2 GOF mutants, but not EZH2 WT (or LOF), caused changes to 3D morphology in A375 melanoma cells." (PMID 25671303, 2015). "The role played by EZH2 GOF mutations in non-hematopoietic cells, and in particular melanoma cells, is completely uncharacterized." (PMID 25671303, 2015). "Importantly, overexpression of miR-31 resulted in downregulation of EZH2 mRNA and protein, and its downstream target MMSET in all three melanoma lines tested." (PMID 22948084, 2012). "Thus, we hypothesized that IκBζ might repress CXCL9, CXCL10, and CCL5 expression through the interaction with EZH2 and/or HDAC3 in melanoma." (PMID 40562773, 2025). "Thus, targeting IκBζ might constitute an attractive approach for sensitizing melanoma patients to immunotherapy, especially as IκBζ deletion would affect multiple oncogenic pathways, including NF-κB, STAT3, EZH2, and HDAC3." (PMID 40562773, 2025).
melanoma (continued). "It has been shown in a mouse model of melanoma that treatment with anti-CTLA-4 antibody or interleukin 2 (IL-2) immunotherapy leads to persistent production of intratumoral tumor necrosis factor alpha (TNF-α) and T cell accumulation, which increases EZH2 expression." (PMID 37325482, 2023). "Therefore, to mimic the clinical scenario, we conducted a long-term clonogenic survival assay using GSK343 (targeting EZH2), JQ1 (targeting BET family BRD proteins-BRD2 and BRD3), TP-472 (targeting BRD7/9) using multiple BRAF mutant melanoma cell lines (M14, SKMEL-28, A375, and A2058)." (PMID 34771678, 2021). "We could neither find a correlation of EZH2 or H3K27me3 expression with a melanoma cell phenotype (e.g., epitheloid or spindle-shaped) or a stronger expression of H3K27me3 in dedifferentiated melanoma cells in vitro." (PMID 32041674, 2020). "In our cohort of 44 melanoma samples prior to immune checkpoint blockade (ICB), we could not find a significant association of H3K27me3 and/or EZH2 expression by IHC with tumor-infiltrating immune cells and response to ICB." (PMID 32041674, 2020). "H3K27me3 is generated by the methylase EZH2(Enhancer of Zesta Homolog-2), which is the catalytic subunit of the polycomb-repressive complex 2 (PRC2) that represses transcription of genes involved in differentiation and tumor suppression in many cancers, including melanoma." (PMID 32731355, 2020). "Silencing of c-Myc by siRNA in three different melanoma cell lines, or treatment of melanoma cells with the c-Myc inhibitor 10058-F4 downregulated FOXM1, EZH2, and H3K27me3, as well as the EMT-related markers ZEB1, N- Cadherin, α-catulin and SNAIL, but upregulated E-Cadherin." (PMID 30710146, 2019). "On this basis and according to available evidence on regulation of FOXM1 by Myc and on regulation and roles of FOXM1 and EZH2 in EMT, we tested the hypothesis that the EMT-like program of melanoma cells could be regulated by an axis connecting NFATc2 to EZH2, through c-Myc and FOXM1." (PMID 30710146, 2019). "MicroRNA miR‐137 acts as tumor suppressor; in fact, the expression of miR‐137 in melanoma leads to the inhibition of the proliferation and invasion by the downregulation of its targets, including MITF, c‐Met, Y‐box‐binding protein 1 (YB‐1) and enhancer of zeste homolog 2 (EZH2)." (PMID 30499222, 2019). "While melanoma cells often behave differently within the tumour microenvironment compared to cultured cells, it is possible that BRN2 and NFIB regulate additional genes that counteract the growth phenotype that might be anticipated with high EZH2 expression." (PMID 28119061, 2017). "In Melanoma, knockdown of BRAFV600E was shown to profoundly reduce the expression levels of EZH2, suggesting that increased BRAF activity frequently found in melanoma may contribute to the abnormal overexpression of EZH2." (PMID 26304929, 2015). "Therefore, we hypothesize that the coordinate regulation of this signaling pathway by EZH2 GOF mutants contributes to the observed collective migration and branching morphology in A375 melanoma cells." (PMID 25671303, 2015). "Similarly, inducible knockdown of EZH2 in a transgenic melanoma mouse model was able to prevent melanoma growth and metastasis, in a manner comparable to the EZH2 inhibitor, GSK503 suggesting a role in melanoma progression." (PMID 26304929, 2015). "Finally, it has been suggested that pharmacological inhibition of histone H3K9 demethylase, either alone or in combination with MAPKi, and co-targeting of EZH2 together with one of its regulators, NFATc2, may benefit the treatment of resistant BRAF V600E melanomas." (PMID 34440824, 2021).
melanoma (continued). "Moreover, treatment of melanoma cell lines with GSK126 alone did not restore the expression of EZH2 target genes, and there was no significant change in DNA methylation in TSG promoter regions, which proves that DNA hypermethylation inhibits the expression of EZH2 target genes in melanomas." (PMID 32751889, 2020). "Hence, it could be concluded that EZH2 lowers the expression of CDKN1C by facilitating H3K27 trimethylation thereby facilitating melanoma cell viability and inhibiting oxidative stress and apoptosis of melanoma cells." (PMID 32308561, 2020). "Given a more than 60% frequency of genomic and non-genomic somatic activation of EZH2 in melanoma patients, this case of precision medicine might be more generalizable and synergy between epigenetic and immune checkpoint inhibition has a strong potential for a broader treatment regimen." (PMID 28265786, 2017). "For example, simultaneous knockdown of EZH2 and its target WDR19 reversed cell cycle arrest, whereas that of EZH2 and AMD1 restored the invasion capacity of melanoma cells without reversing the cell cycle-arrest phenotype." (PMID 33024276, 2020). "For example, EZH2 can methylate non-histone substrates such as STAT3 inducing the tumorigenicity in glioblastoma stem-like cells and melanoma." (PMID 27793053, 2016). "This study not only demonstrates the first functional characterization of EZH2 GOF mutants in non-hematopoietic cells, but also provides a rationale for EZH2 catalytic inhibition in melanoma." (PMID 25671303, 2015). "Tumor-suppressive and anti-metastatic roles of UBE2L6 in vivo have not been described, and we found are mediated in melanoma by the ubiquitin-conjugating function of UBE2L6, working cooperatively with the E3 ligase UBR4, to induce EZH2 ubiquitination and protein degradation." (PMID 36906655, 2023). "Thus, a simple EZH2 inhibitor is not a suitable alternative for solid tumor, such as the BRAF inhibitor resistance melanoma treatment." (PMID 33849069, 2021). "It was noticeable that immune-regulated genes were absent in melanoma with high ATRX levels, which may indicate retargeting of EZH2 to immune gene sets." (PMID 32731355, 2020). "Thus, our results support a model in which IκBζ-mediated recruitment of EZH2 and HDAC3 represses Cxcl10, Cxcl9, and Ccl5 in melanoma, contributing to the observed lack of T-cell infiltration and immunotherapy resistance in the α-PD-1-treated, IκBζ-expressing melanoma mouse models." (PMID 40562773, 2025).
glioma (257 papers, 2010 to 2025). A benign or malignant brain and spinal cord tumor that arises from glial cells (astrocytes, oligodendrocytes, ependymal cells). "ZDHHC5 overexpression in gliomas is linked to the palmitoylation of EZH2, resulting in reduced EZH2 phosphorylation and lower H3K27me3 levels." (PMID 40180214, 2025). "Aberrant EZH2 expression or mutations play pivotal roles in tumor malignant progression, exhibiting high expression in various solid tumors such as glioma and breast cancer, thereby promoting tumor occurrence and development." (PMID 38886655, 2024). "Beyond its association with poor prognosis, MELK activates EZH2 through phosphorylation to promote glioma stem-like cells to proliferate and self-renew." (PMID 38183103, 2024). "In the univariate analysis, high EZH2 protein expression was a strong independent predictor of poor 5-year PFS in patients with gliomas, with a higher risk of recurrence (hazard ratio of 5.841 with 95% confidence interval 2.231–15.292, p < 0.0001)." (PMID 36292072, 2022). "The fact that wild-type IDH1 is causally related to clinical cases of low-grade gliomas lends support to our own findings of its upregulation in the Ezh2 gain-of-function ‘tumors’, presenting similar features." (PMID 35395831, 2022). "EZH2 is also associated with glioma proliferation and metastasis and has been regarded as a potential predictor and therapeutic target in glioma." (PMID 36230759, 2022). "Overall, the H3.3K27M mutation in high-grade glioma is a potential biomarker for poor prognosis mainly due to the infiltration of glioma cells that is at least partially mediated by the β-catenin/USP1/EZH2 pathway." (PMID 36230759, 2022). "To evaluate the association of EZH2 expression within the glioma microenvironment, we evaluated the ImmuneScore, StromalScore or ESTIMATEScore." (PMID 33277782, 2021). "They further identified an EZH2/miRNA/β-catenin feedforward loop associated with the oversecretion of EZH2, β-catenin, and miRNA repression in glioma glucose metabolism." (PMID 34745848, 2021). "Studies further demonstrated that the blockade of EZH2 secretion by shRNA was associated with a substantial reduction in the proliferation of glioma cells." (PMID 34745848, 2021). "EZH2 inhibitor, Tazemetostat, alone, and in conjunction with other therapies, is currently in clinical trials for treating pediatric glioma with EZH2, SMARCB1, or SMARCA4 mutations (ClinicalTrials.gov IDs NCT03213665, NCT03155620)." (PMID 34168976, 2021). "EZH2 overexpression is associated with poor GBM prognosis, and reducing levels of EZH2 expression in vivo resulted in a reduced tumor progression, which suggests the efficacy of EZH2 inhibitors as anti-glioma therapies." (PMID 34168976, 2021). "On the other hand, PVT1 lncRNA expression is increased in glioma tissue, is positively associated with poor outcomes and alters EZH2 expression." (PMID 34316694, 2021). "We evaluated immune checkpoints that are known to be involved in glioma and calculated the association of these immuno‐checkpoints with EZH2." (PMID 33277782, 2021). "It was revealed that telomerase reverse transcriptase (TERT) and EZH2 jointly stimulated PCG-1α resulting in the secretion of fatty acid synthase (FASN) in glioma having (TERT) promoter mutations." (PMID 34745848, 2021). "Currently, two clinical trials are testing the efficacy of tazemetostat (EZH2 inhibitor) in pediatric glioma with rare gain-of-function mutation of EZH2 or loss-of-function mutation of SMARCB1 or SMARCA4, chromatin remodeling subunits." (PMID 32183227, 2020). "Overexpression of EZH2 has proto-oncogenic implications in several cancers, including glioma, in which elevated EZH2 expression has been associated with high-grade disease and poor overall survival." (PMID 33344253, 2020). "That only H3K27M oncohistones deposited during DNA replication are toxic to EZH2 activity also explains why particular secondary mutations are associated with either H3.1K27M- or H3.3K27M-bearing gliomas." (PMID 32902381, 2020).